EZH2 (enhancer of zeste 2 polycomb repressive complex 2 subunit)
Diseases named in the same sentence as EZH2 in open-access papers (continued):
Sharing a sentence is not in itself a finding about the gene and the disease.
prostate carcinoma (continued). "The Whitte laboratory demonstrated a synergistic interaction between Ras pathway activation and AR signaling that leads to elevated EZH2 expression and expand prostate cancer progenitor cells in vivo." (PMID 29888169, 2018). "Recent reports also suggest an important role for EZH2 in the epigenetic control of prostate cancer through modulation of TSG expression." (PMID 28758948, 2017). "In a castration-resistant prostate cancer model, EZH2 acted as a co-activator for critical transcription factors including the androgen receptor (AR) that was independent of its transcriptional repressor function." (PMID 28410242, 2017). "EZH2 is upregulated in prostate cancer through amplification of the EZH2 gene, deletion of its negative regulator miR-101, and transcriptional regulation by MYC and ETS gene family members." (PMID 28758948, 2017). "A prominent member of this complex is an enhancer of zeste homolog 2 (EZH2), which is overexpressed in various cancer types, including prostate cancer where its elevated levels correlate with disease progression and higher Gleason score." (PMID 28486411, 2017). "The role of EZH2 in cancer was first observed when it was identified as one of the top upregulated genes in aggressive prostate cancer." (PMID 28410242, 2017). "Our data suggest that EZH2-directed methylation alterations are critical for the formation and maintenance of prostate cancer, in addition to roles EZH2 plays in castration-resistant prostate cancer." (PMID 28412973, 2017). "GSK926 and GSK-343 inhibit EZH2 activity to suppress histone H3K27me3 level in breast and prostate cancer cells." (PMID 28561778, 2017). "GR expression is silenced in prostate cancer by a combination of AR binding and EZH2-mediated repression at the GR locus, but is restored in advanced prostate cancers upon reversion of both repressive signals." (PMID 28891793, 2017). "The clinical expression of these genes in tumor tissues further verified the regulatory mechanism of HOTAIR/EZH2/miR-193a feedback loop in prostate cancer." (PMID 29141691, 2017). "Together, this indicates that N-MYC cooperates with EZH2 to drive the neuroendocrine phenotype in prostate cancer, thereby providing a rationale for therapeutic strategies targeting EZH2." (PMID 28505071, 2017). "A recent study showed that a transcriptional repressor, ZFN217 interacted with EZH2 to enhance H3K23me3 levels of FPN promoter to promote prostate cancer growth." (PMID 28410242, 2017). "We identified 43 cell-differentiation markers targeted by PRC2 (either showing EZH2-repression in prostate cancer or PRC2-silencing in ESC), presenting a significant enrichment among RA-induced genes and PRC2-silencing targets (p = 1e-8, odds ratio = 3)." (PMID 28984200, 2017). "The H3K27me3 repressive mark has been found on many gene promoters that are silenced, and genome-wide profiling studies of the H3K27me3 mark in metastatic and prostate cancer cells suggest a silencing function of EZH2 in prostate cancer." (PMID 28403887, 2017). "Of these, three (let-7, miR-361 and miR-378) were upregulated by EZH2 knockdown in DU145 prostate cancer cells, and were selected as the top candidates for further investigation." (PMID 28088786, 2017). "As a histone trimethyltransferase, EZH2 represses transcription of a number of tumorigenesis and metastasis suppressor genes thereby regulating prostate cancer development." (PMID 28410242, 2017). "In a castration-resistant prostate cancer model, EZH2 methylated AR and modulated AR recruitment to its target sites." (PMID 28410242, 2017). "Here, we identified a HOTAIR-triggered feedback loop that involves EZH2-mediated repression of miR-193a and controls tumorigenesis and prostate cancer progression." (PMID 29141691, 2017). "The lncRNA, DANCER represses TIMP2/3 expression by mediating the binding of EZH2 on their promoters thereby promoting prostate cancer invasiveness." (PMID 28410242, 2017).
prostate carcinoma (continued). "Dysregulation of the EZH2 gene has been observed in several types of cancers, including lung, breast, and prostate cancer." (PMID 29202777, 2017). "The lncRNA MALAT1 interacts with the N-terminal of EZH2 to enhance migration and invasion in castration-resistant prostate cancer." (PMID 28410242, 2017). "Knockdown of BRAF directly downregulates EZH2 gene expression in melanoma cells and prostate cancer." (PMID 29202777, 2017). "These neoplasms were, in addition to breast and prostate cancer, pioneering models for investigating the function and role of EZH2." (PMID 27239242, 2016). "In prostate cancer, several miRNAs that are repressed by EZH2 were identified, such as miR-181a, miR-181b, miR-200b, miR-200c and miR-203." (PMID 27385092, 2016). "EZH2 reportedly downregulates miR-31 expression in human cancers such as prostate cancer and adult T-cell leukemia." (PMID 26871294, 2016). "Overexpression of both UHRF1 and EZH2 coordinately suppressed antitumor genes and contributed to prostate cancer pathogenesis and metastasis." (PMID 27487138, 2016). "Combination of the EZH2 inhibitor GSK126 with etoposide in prostate cancer led to accumulation of DNA damage and increased the apoptotic rates compared to each monotherapy." (PMID 27793053, 2016). "EZH2 has also been shown to be a critical regulator of stem cell functionality, radio-resistance, and prostate cancer aggressiveness." (PMID 27340920, 2016). "It has been found that the over expression of EZH2 leads to a number of cancer with elevated levels of EZH2 found in breast as well as prostate cancer patients." (PMID 27713574, 2016). "EZH2 can also methylate AR in prostate cancer promoting its chromatin binding and the up-regulation of AR downstream targets." (PMID 27793053, 2016). "The relevance of EZH2 in human prostate cancers is first evident by the finding that expression of EZH2 is highly upregulated in metastatic CRPC relative to the benign prostatic tissues and primary PCa." (PMID 26657505, 2016). "A recent study has reported that EZH2 suppresses miR-31 expression by inducing H3K27me3 on the miR-31 promoter and that the inhibition of EZH2 increased miR-31 expression in prostate cancer." (PMID 26871294, 2016). "In fact, CDKN2A, ADRB2, CDH1 and SLIT2 were reported to be suppressed by EZH2 in prostate cancer cells and were also targeted by EZH2 in at least one prostate cell line in our ChIP sequencing analysis." (PMID 27835578, 2016). "Conversely, EZH2 has been reported to suppress miR-31 expression by inducing H3K27me3 on the miR-31 promoter in prostate cancer." (PMID 26871294, 2016). "HOTAIR, one of the most well-known and studied lncRNA, was firstly found to recruit PRC2 in modulating the cancer epigenome in prostate cancer which depend on the enzymatic activity of EZH2." (PMID 27835578, 2016). "EZH2 expression in < 1% of tumor cells in prostate cancer biopsies was predictive for indolent disease at radical prostatectomy." (PMID 27191985, 2016). "This H3K27me3-independent function in transcriptional activation has also been observed in breast and prostate cancer, suggesting a possible switch of EZH2 from silencer to activator during tumorigenesis in some cancers." (PMID 26497210, 2016). "It is indeed possible that EZH2 and miR-99a/100 can collaborate in regulating prostate cancer stem cell functionality and radiation-sensitivity." (PMID 27340920, 2016). "In prostate cancer cells, EZH2 interacts with androgen receptor (AR) independently of PRC2, and functions as a transcriptional co-activator inducing the expression of AR target genes." (PMID 27793053, 2016). "Recently, Wee’s13 and Zhang’s36 work demonstrated inhibition of EZH2 expression induced apoptosis in prostate cancer, however, Rao’s24 study indicated inhibition of EZH2 expression did not affect apoptosis of ovarian carcinoma." (PMID 26265454, 2015).
prostate carcinoma (continued). "In clinical prostate cancer samples, the RUNX1 expression level is negatively associated with EZH2 and that RUNX1 loss correlated with poor prognosis." (PMID 25537508, 2015). "Using two mouse models of prostate cancer and one model of mammary tumorigenesis, we found that EZH2, although highly up-regulated in cancerous tissue, is dispensable for tumor progression." (PMID 26637281, 2015). "The top-enriched signature is that of genes up-regulated upon EZH2 knock-down in prostate cancer cells (Poverlap = 3.61 × 10−9)." (PMID 26191074, 2015). "The Polycomb protein enhancer of zeste homolog 2 (EZH2) is frequently overexpressed in advanced human prostate cancer (PCa), especially in lethal castration-resistant prostate cancer (CRPC)." (PMID 26516927, 2015). "Second, H1.2 can localize at several growth suppressive genes in a manner dependent on EZH2 which is primarily responsible for H3K27me3 in breast, bladder, and prostate cancer cells." (PMID 26581166, 2015). "In contrast, we observed strong expression of EZH2 in the nucleus of prostate cancer tissues, and weak expression in benign prostate tissues surrounding cancerous regions." (PMID 25537508, 2015). "We also observed that repression of RUNX1 by EZH2 enhanced androgen-independent prostate cancer cell growth." (PMID 25537508, 2015). "In mouse and human models, EZH2 is dispensable for prostate cancer development and restrains breast tumorigenesis." (PMID 26637281, 2015). "Given the prior links made between Ezh2 overexpression and the more aggressive forms of prostate cancer, we used genetically engineered mouse models of prostate cancer to investigate the role of the enzyme in carcinogenesis." (PMID 26637281, 2015). "In prostate cancer compared to normal prostate, its expression is increased and correlated with increased EZH2 occupancy levels near the INK4a and ARF genes promoters." (PMID 26580594, 2015). "With respect to miRNAs, prior work demonstrates that EZH2 interacts with AR to silence miR-31 in prostate cancers, and C-MYC recruits EZH2 to the miR-29 promoter in B-cell lymphomas." (PMID 25644061, 2015). "We expressed EZH2 exogenously to determine if EZH2 can contribute to apoptosis resistance in prostate cancer cells." (PMID 25341040, 2014). "MiR-124 in turn is negatively regulated by transcriptional repressors EZH2 and CtBP1, both of which are overexpressed in aggressive prostate cancer." (PMID 25115393, 2014). "Here we show that EZH2 also suppresses prostate cancer apoptosis by coordinating the epigenetic silencing of two proapoptotic microRNAs (miRNA), miR-205 and miR-31." (PMID 25341040, 2014). "Collectively, our data indicate a PRC2 dependent mechanism in ID4 promoter silencing in prostate cancer through recruitment of EZH2 and a corresponding increase in H3K27Me3." (PMID 25115397, 2014). "EZH2 enrichment in benign prostate tissue was significantly lower (0.076+0.042) as compared to that in prostate cancer (0.44+0.077, P<0.001)." (PMID 25115397, 2014). "This agrees with observations in other tumors showing that EZH2 is overexpressed in cancers, including melanoma, lymphoma, and breast and prostate cancers." (PMID 24852755, 2014). "Here, we report, to our knowledge for the first time, that ID4 is a PcG (Polycomb group) protein EZH2 target gene in prostate cancer." (PMID 25115397, 2014). "The PC3 prostate cancer cells were transiently transfected with either vector or EZH2 plasmids, and then followed by NSC745885 treatment." (PMID 25431950, 2014). "In prostate cancer, the upregulation of EZH2 in high grade and metastatic disease represses miR-203, which targets MMSET, explaining, at least in part, MMSET upregulation." (PMID 25188243, 2014). "Certainly, EZH2 was overexpressed in prostate cancer and played a crucial role in several steps of the metastatic process as described in previous studies." (PMID 25535400, 2014).
prostate carcinoma (continued). "The enhancer of zeste homologue 2 (EZH2) gene is overexpressed in prostate cancer and interacts with DNA methyl transferases to influence DNA methylation." (PMID 25496077, 2014). "In another prostate cancer cell line DU-145, we also observed that siRNA knockdown of EZH2 or DZNeP treatment increased miR-31 expression and decreased E2F6." (PMID 25341040, 2014). "Fitting together the scattered pieces of this jigsaw puzzle indicates that the disturbance of miRNA mediated regulation of ERG and EZH2 in prostate cancer requires detailed investigation." (PMID 24739220, 2014). "Laser capture micro-dissected prostate cancer and benign prostate tissue was used to further investigate EZH2 dependent histone modifications." (PMID 25115397, 2014). "In paired human prostate cancer specimens and adjacent normal tissues, we observed that the decrease of miR-205 expression correlated with EZH2 overexpression and miR-31 silencing." (PMID 25341040, 2014). "MiR-124 in turn is regulated by transcriptional repressor Enhancer of Zeste Homolog 2 (Drosophila) EZH2 and transcriptional co-repressor C-terminal binding protein 1 (CtBP1), genes that are overexpressed in aggressive prostate cancer." (PMID 25115393, 2014). "ChIP data on prostate cancer tissue specimens and cell lines suggested EZH2 occupancy and H3K27Me3 marks on the ID4 promoter." (PMID 25115397, 2014). "The loss of let-7 family was also found to be inversely correlated with increased expression of EZH2 in prostate cancer tissues compared to adjacent normal prostate tissues." (PMID 25254214, 2014). "Overexpression and amplification of EZH2 is barely detected in early stage of prostate cancers, but is more general in late stages." (PMID 25520914, 2014). "EZH2 plays a critical role in cell fate determination and its increased expression is observed in many cancers, including prostate cancer." (PMID 25115397, 2014). "They revealed that ERG promotes prostate cancer progression by working together with transcriptional corepressors including HDACs and EZH2." (PMID 23957008, 2013). "Numerous studies suggest that EZH2 is aberrantly overexpressed in several types of cancer, particularly metastasic breast and prostate cancer, and EZH2 overexpression promotes cell proliferation, invasion and metastasis." (PMID 23599767, 2013). "Although EZH2 plays a key role during embryogenesis and in a variety of adult stem cells, little is known regarding the influence of EZH2 on prostate cancer stem cells." (PMID 23739676, 2013). "The miR-26a can be silenced by DNMTs in prostate cancer, which induces the accumulation of its target gene EZH2 and changes the global DNA methylation status, supporting the idea that miRNAs can mediate the interplay between epigenetic regulators." (PMID 24261995, 2013). "This study also provided compelling evidence that the oncogenic activity of EZH2 in castration-resistant prostate cancer cells is based on this polycomb independent activity of EZH2." (PMID 23673719, 2013). "Here, we have shown that hypoxia leads to increased expression of VEGF, IL-6, and CSC marker genes such as Nanog, Oct4 and EZH2, and also increased the expression of miR-21, an oncogenic miRNA, in prostate cancer (PCa) cells (PC-3 and LNCaP)." (PMID 22952749, 2012). "To identify metastasis-associated genes whose expressions are regulated by EZH2, we investigated gene expression changes in invasive prostate cancer cells after EZH2 knockdown." (PMID 22272343, 2012). "In this study, we investigated the role of EZH2 in activation of MMPs to promote the invasion and metastasis of prostate cancer cells." (PMID 22272343, 2012). "Because EZH2 plays an active role in prostate cancer invasion, we further examined the migratory activity of DU145 cells using the wound-healing migration assay (top)." (PMID 22272343, 2012). "The pioneering work by Chinnaiyan’s group identified EZH2 protein in many human malignancies, including renal, breast and prostate cancer." (PMID 22641253, 2012).
prostate carcinoma (continued). "The TIMP genes are derepressed by knockdown of EZH2 expression in human prostate cancer cells but repressed by overexpression of EZH2 in benign human prostate epithelial cells." (PMID 22272343, 2012). "Recently, microRNA technology was effectively used to inhibit EZH2 expression resulting in a decreased migratory and invasive ability of prostate cancer cells." (PMID 22641253, 2012). "In this study, we show that aberrant upregulation of EZH2 expression in prostate cancer cells shift this balance towards MMPs and thereby promote degradation of the ECM." (PMID 22272343, 2012). "Specifically, ATRA inhibits the proliferation of DU145 prostate cancer cells through reducing the methylation level of HOXB13 promoter induced by EZH2 and DNMT3b." (PMID 22808286, 2012). "Increased expression of the EZH2 (enhancer of zeste homolog 2) gene has been observed in various aggressive tumors, that is, cancer of the prostate, breast, and bladder." (PMID 23304520, 2012). "We then examined the invasive activity of prostate cancer cells expressing different levels of EZH2 protein using Transwell Boyden chamber assay." (PMID 22272343, 2012). "In multiple types of lymphoma, breast and prostate cancer, the aberrant expression of EZH2 is also indicative of poor prognosis and metastatic tumor." (PMID 22348393, 2012). "In contrast, EZH2 protein levels were very high in prostate cancer tissues compared with normal prostate tissues." (PMID 22272343, 2012). "The functional role of EZH2 in prostate cancer progression has been identified by gene expression profiling of RNA from nontumorigenic human prostate epithelial cells overexpressing EZH2." (PMID 22272343, 2012). "Here, we identify EZH2 as a target of the MYC oncogene in prostate cancer and show that MYC coordinately regulates EZH2 through transcriptional and post-transcriptional means." (PMID 21941025, 2011). "miR-101 was shown to specifically target EZH2 for down regulation in prostate cancer cells, and the miR-101 locus was deleted in 37.5% of localized prostate cancers and 66.7% of castrate-resistant metastatic prostate cancer cases." (PMID 21941025, 2011). "Next, we obtained mRNA from 18 matched normal and primary prostate cancer specimens and confirmed that MYC and EZH2 mRNA were indeed overexpressed in the prostate cancers (Wilcoxon signed ranked test, p<0.0002 for both)." (PMID 21941025, 2011). "EZH2 is amplified and overexpressed in prostate cancer, with moderate increases in localized tumors, and higher expression in metastatic prostate cancers." (PMID 22191037, 2011). "It has been shown that EZH2 is overexpressed in prostate cancer, particularly in aggressive metastatic cases." (PMID 21941025, 2011). "Using 5 prostate cancer cell lines (4 human, 1 mouse), we showed that Myc depletion by siRNA results in decreased EZH2 mRNA and protein." (PMID 21941025, 2011). "EZH2 is overexpressed during prostate cancer progression and promotes proliferation, invasion, tumor formation, and metastasis of prostate cancer cells, and is considered to be involved in the progression to advanced disease." (PMID 21941025, 2011). "To determine if mir-26a and miR-26b can target EZH2 in prostate cancer cells, we transfected miR-26a and miR-26b mimics into one mouse and four human prostate cancer cell lines." (PMID 21941025, 2011). "In prostate cancer cells, we found that both miR-26a and miR-26b repressed both EZH2 mRNA and protein." (PMID 21941025, 2011). "EZH2 mRNA and protein levels are elevated during progression of a number of types of cancer, including breast and prostate cancer." (PMID 21941025, 2011). "EZH2 is part of the PRC2 polycomb repressive complex that is overexpressed in multiple cancer types and has been implicated in prostate cancer initiation and progression." (PMID 21941025, 2011).